MFN2 (mitofusin 2)
Diseases named in the same sentence as MFN2 in open-access papers (continued):
Sharing a sentence is not in itself a finding about the gene and the disease.
Obesity (continued). "To determine whether obesity‐induced BAT remodeling was different in Mfn2‐deleted BAT, we characterized mitochondria from BAT‐Mfn2‐KO males and females fed a HFD at 22°C." (PMID 28539390, 2017). "Defects of Mfn2 were found in diabetes, obesity, and neurodegenerative diseases." (PMID 25781899, 2015). "Indeed, under diet-induced obesity (DIO) conditions hypothalamic Mfn2 expression was reduced and its overexpression in the ARC was able to ameliorate the metabolic disturbances and reduce ER stress markers in the hypothalamus of DIO mice." (PMID 26113818, 2015). "In this study we evaluated the mechanism(s) of mitochondrial alterations in an animal model of obesity (ob/ob mice) and describe the beneficial effects of melatonin treatment on mitochondrial morphology and dynamics as influenced by mitofusin-2 and the intrinsic apoptotic cascade." (PMID 25347680, 2014). "A mitochondrial reduction in membrane potential and fragmentation may be related to Mfn2 expression during obesity." (PMID 25347680, 2014). "A series findings by Zorzano's group also showed that altered expression of OPA1 and decreased expression of MFN2 participated in the development of obesity and type 2 diabetes in both patients and rodent models, which highlighted the importance of MFN2 in metabolism." (PMID 24658162, 2014). "Moreover, Mfn2 levels were lower in the myocardium of patients with obesity than in controls." (PMID 38311582, 2024). "Defective MFN2 mutants have been associated with development of Charcot-Marie-Tooth disease type 2A (CMT2A) and imbalances in mitochondrial dynamics have been linked to metabolic disorders such as type II diabetes, obesity, neurodegeneration, cancer, and aging." (PMID 35798717, 2022). "Similar effects of diminished MFN2 expression were observed in the liver and muscle cells in animal models of high-fat diet-induced obesity and insulin resistance, which supports the hypothesis that MFN2 can affect insulin signaling and insulin sensitivity through mitochondria-related mechanisms." (PMID 33815291, 2021). "This study also showed that, in the HFD-Con group, where obesity was induced, the expression of proteins related to mitochondrial fission, Drp1 and Fis1, increased, whereas the expression of proteins related to mitochondrial fusion, Mfn1, Mfn2, and Opa1, decreased." (PMID 31010272, 2019). "Moreover, selective Mfn2 ablation in pro‐opiomelanocortin (POMC) neurons in the hypothalamus resulted in loss of ER–mitochondria contact sites, ER stress‐induced leptin resistance, reduced energy expenditure, and obesity." (PMID 29068134, 2018). "On the other hand, mice with a POMC-specific deletion of MFN2 (mitofusin 2), a key protein for mitochondrial fusion and the formation of ER–mitochondria contacts, display a loss of these interactions, defective POMC processing, ER stress-induced leptin resistance, and obesity." (PMID 28270795, 2017). "In this regard, BAT-specific Mfn2 deletion decreased the animal energy efficiency and increased coupled fat oxidation in BAT, explaining protection from obesity and hyperglycemia." (PMID 34741717, 2022). "On the other hand, others and we have reported up regulation of hypothalamic MFN2 protein levels of obese mice, and defective MFN2-expression in POMC or Agrp neurons promotes or prevents obesity in a rodent obese model, respectively." (PMID 29991958, 2018). "Similar to the BAT‐Mfn2‐KO mice we describe here, the adipo‐Mfn2‐KO show defective thermogenesis, BAT lipohypertrophy and improved glucose tolerance after diet‐induced obesity." (PMID 28539390, 2017). "Surprisingly however, deletion of Mfn2 in mice fed a high fat diet (HFD) results in improved insulin sensitivity and resistance to obesity, while impaired cold‐stimulated thermogenesis is maintained." (PMID 28539390, 2017). "Unlike the effects in AgRP neurons, genetic ablation of Mfn2 in POMC neurons results in severe obesity characterized by overeating, low energy expenditure, and endocrine dysregulation." (PMID 35898328, 2022).
Obesity (continued). "The DNM1L, MFN2, and TFAM gene expression levels in GO and SAT responsible for regulating mitochondrial dynamics were increased in obese patients without T2DM, and DNM1L and TFAM proteins production were unbalanced in patients with obesity and T2DM." (PMID 34572446, 2021). "Deletion of Mfn1 or Mfn2 in AgRP/NPY neurons prevents fusion and impairs neuronal firing frequency in diet-induced obesity, illustrating that the induction of mitochondrial fusion is required for the paradoxical neuronal activation of AgRP/NPY neurons following exposure to HFD (Figure 2Cii)." (PMID 33240218, 2020). "Interestingly, Mfn2 and Ucp1 show striking similarities in their effects on BAT response to cold and obesity." (PMID 28539390, 2017). "Thirdly, ablation of either Ucp1 or Mfn2 changes the overall metabolic response to diet‐induced obesity in the absence of thermal stress." (PMID 28539390, 2017). "In all, these data suggested that mitochondrial dynamics, namely Mfn1 and Mfn2, in NPY/Agrp and POMC neurons may play a role in the central regulation of energy balance and in etiology of diet induced obesity." (PMID 25904870, 2015). "However, the absence of Mfn2 in AgRP neurons can prevent adverse metabolic responses, reduce fat mass, restore insulin and blood glucose levels, and prevent obesity." (PMID 39763653, 2024). "This increase in fusion (MFN1 and MFN2) and decrease in fission (FIS1) contribute to an increase in overall mitochondrial function, leading to a decrease in adiposity in HF fed mice, a consequent reduction in obesity, and a concurrent reduction in the development of NASH." (PMID 30057822, 2018). "Therefore, absence of Mfn2 in BAT was not protecting from obesity in males, but rather reducing total lean mass." (PMID 28539390, 2017). "Thus, BAT adaptation to obesity is regulated by Mfn2 and with BAT‐Mfn2 absent, BAT contribution to prevention of insulin resistance is independent and inversely correlated to whole‐body cold‐stimulated thermogenesis." (PMID 28539390, 2017). "HFD results in a downregulation of Mfn2 expression, increased mitochondrial density, and decreased mitochondria–ER contacts in POMC neurons, illustrating that MFN2 is involved in metabolic alterations following diet-induced obesity and so may be involved in the central regulation of energy balance." (PMID 33240218, 2020). "As part of the mitochondrial fusion machinery, mitofusin 1 and 2 (MFN1 and MFN2, respectively) were significantly increased by DPR, irrespective of obesity, whereas optic atrophy 1 (OPA1) expression was unchanged." (PMID 41549510, 2026). "While another study found Mfn1 and Mfn2 but not Opa1 were decreased, and Drp1 and Fis1 were increased in skeletal muscle of HFD-induced obesity mice." (PMID 29245950, 2017). "On the other hand, mice lacking Mfn2 specifically in AgRP neurons do not display any morphological or molecular signs of ER stress or inflammation in the hypothalamus, and they are surprisingly resistant to HFD-induced obesity." (PMID 33092099, 2020). "Mfn2, but not Mfn1, deletion in brown adipose tissue (BAT) remodels the mitochondrial dysfunction, leading to an increase in insulin sensitivity and resistance to obesity." (PMID 31551926, 2019). "However, the role of Mfn2 in obesity‐induced BAT remodeling and the effect of chronically reducing Mfn2 in BAT in vivo have not been explored." (PMID 28539390, 2017).
cardiac hypertrophy (59 papers, 2015 to 2025). "Here, as part of an ongoing effort to understand the relationship between MFN2 mutation site, protein dysfunction, and disease manifestation, we screened cardiomyopathy research cohorts for MFN2 mutations linked to cardiac hypertrophy or heart failure." (PMID 37910431, 2023). "Cardiac-specific MFN2 depletion is associated with moderate myocardial hypertrophy and mild functional deterioration in mice." (PMID 36337896, 2022). "Mfn1 and Mfn2 as regulators of mitochondrial size have been demonstrated in numerous studies, and hearts deficient in Mfn2 exhibit cardiac hypertrophy and have small fragmented IFM40." (PMID 35046471, 2022). "Although there is limited literature that decodes the function of Mfn2 in heart failure, it has been reported that Mfn2 has associated with the onset and progression of cardiac hypertrophy and heart failure." (PMID 34026850, 2021). "Mfn2-deficient mice display enlarged cardiomyocytes and modest cardiac hypertrophy with functional deterioration." (PMID 32104528, 2020). "Mfn1/Mfn2 deficient mice and Tmem135 TG mice show cardiac hypertrophy while mice with induced processing of OPA1 develop dilated cardiomyopathy." (PMID 30102730, 2018). "Notably, MFN2 loss was associated with myocardial hypertrophy in cardiac tissue, while gene delivery of an adenoviral vector‐encoding rat MFN2 proved to successfully protect against myocardial hypertrophy." (PMID 40285369, 2025). "Overexpression of MFN2 suppressed cardiac hypertrophy caused by angiotensin II." (PMID 36337896, 2022). "We found one report suggesting that miRNA106a may cause cardiac hypertrophy by targeting and suppressing mitofusin 2 (Mfn2), a mitochondrial membrane protein involved in maintaining mitochondrial structure." (PMID 35890169, 2022). "Besides, Mfn2 expression is associated with proliferation and apoptosis of VSMCs and myocytes in cardiac hypertrophy." (PMID 34026850, 2021). "Moreover, a deficiency of mitochondrial fusion inducer Mfn2 further showed cardiac hypertrophy and reduced cardiac function." (PMID 34912235, 2021). "Cardiomyocytes of Mfn2-deficient mice showed cardiac hypertrophy." (PMID 33260800, 2020). "The luciferase reporter system has confirmed that Mfn2 is a target gene of miR-195-5p, which negatively regulates Mfn2 expression in H9c2 cells and promotes cardiac hypertrophy." (PMID 40520935, 2025). "In contrast, 8 weeks of aerobic exercise and choline intervention inhibited myocardial MFN2 expression, attenuated cardiac hypertrophy, and improved cardiac function in damaged cardiac tissue after aortic constriction." (PMID 40520935, 2025). "Analogously, an opposing study indicated that lncRNA ZNF593-AS inhibits cardiac hypertrophy and myocardial remodeling by upregulating MFN2 expression." (PMID 40520935, 2025). "In contrast, upregulation of Mfn2 expression ameliorated cardiac hypertrophy induced by angiotensin II." (PMID 40520935, 2025). "Consistent with this, Mfn2-KO mice exhibited moderate cardiac hypertrophy and mild functional deterioration, suggesting mild mitochondrial dysfunction." (PMID 40520935, 2025). "Mfn2 expression is downregulated in cardiac hypertrophy; however, Mfn upregulation via viral mRNA modulates myocyte hypertrophy." (PMID 39335620, 2024). "Xieet al. reported that USP28 regulates mitochondrial homeostasis via the PPARα-Mfn2 axis and modulates cardiac hypertrophy in diabetic cardiomyopathy." (PMID 39210825, 2024). "Drp1 and YAP, which can regulate mitochondria through SIRT1/MFN2, can reduce gastric cancer survival and migration, and attenuate mitochondrial dysfunction in cardiac hypertrophy." (PMID 37895915, 2023). "Previous studies have revealed that the conditional deletion of cardiac Mfn2 leads to mitochondrial dysfunction and results in myocardial hypertrophy and dysfunction." (PMID 36609664, 2023).
cardiac hypertrophy (continued). "In contrast to cardiomyocytes with fusion defects due to Mfn1/Mfn2 knockout or fission defects due to Drp1 knockout, the Mfn1/Mfn2/Drp1 triple knockout cardiomyocytes exhibit prolonged survival and overt cardiac hypertrophy." (PMID 37895224, 2023). "The reports on miRNA involvement in the regulatory network of cardiovascular disease have shown the upregulation of miR-106a in cardiac hypertrophy, and mitofusin 2 (Mfn2) was identified as the potential target gene for this miRNA." (PMID 37627777, 2023). "In pathological cardiac hypertrophy, miR-17-5p can accelerate the degeneration of cellular hypertrophy by mediating Mfn2." (PMID 36882677, 2023). "Mfn2 is located in the mitochondrial outer membrane and serves as a negative regulator of cardiac hypertrophy by participating in mitochondrial fusion." (PMID 37796408, 2023). "In vivo and in vitro studies showed MFN2 downregulation such as cardiac hypertrophy which is induced by pressure overload." (PMID 36337896, 2022). "In both models of TAC-induced cardiac hypertrophy of mice and TGFβ-induced cardiomyogenic fiber activation assay in vitro, the expression of MFN2 decreased." (PMID 36588561, 2022). "Mfn2 KO mice have mild mitochondrial dysfunction and display modest cardiac hypertrophy and slight functional deterioration." (PMID 35665261, 2022). "The expression level of Mfn2 was decreased in neonatal rat ventricular myocytes treated with phenylephrine, which contributed to the induction of cardiac hypertrophy." (PMID 35665261, 2022). "For instance, MFN2 expression was found to be reduced in rat models of cardiac hypertrophy, and rats with spontaneous hypertension, transverse aortic banding, and myocardial infarction." (PMID 36337896, 2022). "Plscr4 negatively regulates cardiac hypertrophy by sponging miR-214, which suppresses the expression of Mitofusin 2 (Mfn2)." (PMID 35990951, 2022). "Another study showed that MFN2 was downregulated in a rat model of myocardial hypertrophy, depending on the etiology and time course of myocardial hypertrophy." (PMID 35783853, 2022). "Many miRNAs are thought to be involved in the development of CVDs, such as miR-20b, which promotes cardiac hypertrophy by targeting the inhibition of mitofusin 2 (MFN2)-mediated intercellular Ca2+ interactions in cardiomyocytes." (PMID 34122082, 2021). "Vivo studies demonstrated that specific deletion of Mfn2 in cardiomyocytes impaired mitochondrial fusion and modest cardiac hypertrophy." (PMID 34026850, 2021). "MiR-195-5p stimulates cardiac hypertrophy through mitofusin-2 (MFN2) and F-box and WD Repeat Domain Containing 7 (FBXW7) and upregulates angiotensin II (Ang II)." (PMID 34527667, 2021). "Cardiac-specific MFN2 knockout mice displayed cardiac hypertrophy and moderate diastolic dysfunction." (PMID 34336092, 2021). "Both miR-106a and miR-20b can induce mitochondrial dysfunction and promote cardiac hypertrophy by inhibiting the expression of MFN2." (PMID 34122082, 2021). "Recently, genetic ablation mice are used to explore the function of Mfn2 in cardiac hypertrophy and heart failure." (PMID 34026850, 2021). "A recent study showed that microRNA-20b can downregulate Mfn2 and promote cytoplasmic Ca2+ overload, thus, weakening the buffering capacity of mitochondria and increasing cardiac hypertrophy." (PMID 34660720, 2021). "Mfn2 plays a critical mediator in the development of cardiac hypertrophy and heart failure via regulation of various biological processes, including mitochondrial fusion, mitophagy, and apoptosis." (PMID 34026850, 2021). "Cumulatively, these results indicate that Mfn2 is a necessary component for cardiac hypertrophy and heart failure." (PMID 34026850, 2021). "Downregulation of MFN2 has been observed in rat models of cardiac hypertrophy, including spontaneously hypertensive rats, transverse aortic banding, and myocardial infarction, which contribute to cardiomyocyte remodeling." (PMID 34336092, 2021).
cardiac hypertrophy (continued). "MiR-485-5p can improve mitochondrial fission and reverse cardiac hypertrophy by activating MFN2 and causes the downregulation of mitochondrial anchored protein ligase (MAPL) in phenylephrine (PE)-induced cardiac hypertrophy models." (PMID 34122082, 2021). "Changes in Mfn2 expression in cardiac hypertrophy have been studied in several disease models—from spontaneously hypertensive rats to pressure-overload hypertrophy caused by transverse aortic constriction (TAC)." (PMID 33392184, 2020). "Recent studies have shown a key negative regulator role by MFN2 in cardiac hypertrophy via inhibiting mitochondrial membrane depolarization and ROS (reactive oxygen species) production." (PMID 31341888, 2019). "Upregulation of Mfn2 inhibited angitensin-II induced myocardial hypertrophy by inhibiting Akt signaling." (PMID 31178957, 2019). "In TAC-operated mice model, lncRNA Plscr4 forced expression was indicated to attenuate cardiac hypertrophy by sponging miR-214 and further upregulating mitofusin 2 (Mfn2) expression, a critical modulator of mitochondrial homeostasis." (PMID 31355277, 2019). "Mitofusin 2 (Mfn2), which is located at the mitochondrial outer membrane, plays a negative regulator of cardiac hypertrophy by modulating mitochondrial fusion." (PMID 30305865, 2018). "Recent studies using a double KO of Mfn1 and Mfn2 and triple KO of Mfn1, Mfn2, and Drp1 mouse model demonstrated that the complete ablation of mitochondrial dynamics results in cardiac hypertrophy and HF due to diminished mitophagy." (PMID 30131726, 2018). "Mfn2 knockout mice exhibited increased mitochondrial size, dissipation of mitochondrial inner membrane potential, and increased ROS generation; cardiac hypertrophy and ventricular dysfunction occurred in older Mfn2 knockout mice." (PMID 25652199, 2015). "Furthermore, upregulation of MFN2 has been shown to inhibit angiotensin II-induced cardiac hypertrophy, with the inhibition of AKT activation playing a significant role in this process." (PMID 40520935, 2025). "The lncRNA Plscr4 blocks the development of cardiac hypertrophy by targeting the miR-214/Mfn2 axis." (PMID 40874024, 2025). "Mechanistically, miR-17-5p may also contribute to cardiac hypertrophy by inhibiting Mfn2 expression, activating the PI3K/AKT/mTOR pathway, and inhibiting autophagy." (PMID 40520935, 2025). "Similarly, ubiquitin-specific peptidase 2 overexpression mediates deubiquitination to upregulate MFN2, attenuating Ca2+ overload-induced mitochondrial dysfunction and cardiac hypertrophy." (PMID 40520935, 2025). "Target gene prediction programs predicted Mfn2 as a target ofmiRNA-20, indicating that miRNA-20 may participated in theregulation of the occurrence and development of cardiac hypertrophy by interactwith its downstream Mfn2 factor." (PMID 39077079, 2023). "The specific cardiac deletion of Mfn2 leads to cardiac hypertrophy with systolic dysfunction." (PMID 37726810, 2023). "Conversely, MFN2 overexpression alleviated Ang-II induced cardiac hypertrophy." (PMID 36776252, 2023). "Besides, cardiac deletion of MFN2 mice developed cardiac hypertrophy and moderate diastolic dysfunction." (PMID 36776252, 2023). "In our previous study, we found that LncRNA Plscr4 could act as a sponge for miR-214 and mediate the expression of Mfn2 to influence mitochondrial function and regulate the development of cardiac hypertrophy." (PMID 37253771, 2023). "Interestingly, mice with cardiac-specific Mfn1/Mfn2/Drp1 triple KO have a longer life and a unique pathological form of cardiac hypertrophy from that of Mfn1/Mfn2 double KO mice." (PMID 35665261, 2022). "Cardiac-specific MFN2 depletion led to cardiac hypertrophy and moderate diastolic dysfunction." (PMID 36337896, 2022). "Moreover, miR-195-5p and miRNA-20a-5p can promote cardiac hypertrophy via targeting mitofusin-2 (MFN2), which is a mitochondrial outer membrane fusion protein." (PMID 33748196, 2021).